H1-3 (H1.3 linker histone, cluster member)
Description:
Histone H1 protein binds to linker DNA between nucleosomes forming the macromolecular structure known as the chromatin fiber. Histones H1 are necessary for the condensation of nucleosome chains into higher-order structured fibers and promote formation of the H3K27me3 mark by the PRC2/EED-EZH2 complex. Together with histone H1-3, histone H1-3 acts as a regulator of splicing, most specifically exon skipping and intron retention events: histone H1-3 has a high affinity for introns and regulates splicing by affecting RNA polymerase II (RNAPII) elongation. Also acts as a regulator of individual gene transcription through chromatin remodeling, nucleosome spacing and DNA methylation (By similarity).
Synonyms: H1F3; HIST1H1D; H1.3; H1d; H1s-2
Tractability: PROTAC: ubiquitination databases record sites on it.
Gene: Protein-coding gene on chromosome 6 (26,234,212 to 26,234,987, reverse strand). Ensembl gene ENSG00000124575.
Subcellular location: Nucleus; Chromosome
Pathways (Reactome):
Cellular responses to stimuli: Formation of Senescence-Associated Heterochromatin Foci (SAHF)
Programmed Cell Death: Apoptosis induced DNA fragmentation
Gene Ontology:
Molecular function: chromatin DNA binding; protein binding; RNA binding; double-stranded DNA binding; nucleosomal DNA binding; DNA binding; structural constituent of chromatin
Biological process: regulation of mRNA splicing, via spliceosome; chromosome condensation; negative regulation of DNA recombination; nucleosome assembly
Cellular component: chromatin; chromosome; euchromatin; heterochromatin; nucleus; nucleosome
Genetic constraint (gnomAD): Loss-of-function variants: 6 observed, 5 expected, observed/expected ratio (o/e) 1.2, 90% interval 0.63 to 1.88. That is too few expected variants to judge how well the gene tolerates losing a copy. Missense variants: 670 observed, 293.37 expected, observed/expected ratio (o/e) 2.28. Synonymous variants: 266 observed, 118.88 expected, observed/expected ratio (o/e) 2.24.
Homologues: Orthologues: chimpanzee H1-3 (98% identical), macaque H1-3 (95% identical), mouse H1f3 (88% identical), pig H1-3 (87% identical), rabbit H1-3 (87% identical), dog H1-3 (85% identical), rat H4f3 (83% identical), zebrafish si:dkey-23a13.9 (60% identical), zebrafish h1l1 (59% identical), Caenorhabditis elegans hil-3 (26% identical), Caenorhabditis elegans hil-6 (25% identical), Caenorhabditis elegans hil-2 (23% identical), and 2 more. Paralogues in human: H1-4 (86% identical), H1-5 (81% identical), H1-2 (80% identical), H1-1 (67% identical), H1-6 (48% identical), H1-0 (38% identical), H1-8 (33% identical), H1-10 (27% identical), H1-7 (24% identical).
Diseases named in the same sentence as H1-3 in open-access papers:
H1-3 is named in the same sentence as 21 diseases in open-access papers, as found by Europe PMC text mining. Sharing a sentence is not in itself a finding about the gene and the disease.
H1-3 shares sentences with these, for which no sentence is quoted: cancer (6 papers); pancreatic cancer (3); tumor (3); ovarian carcinoma (2); acute myeloblastic leukemia (1); adenocarcinoma (1); benign tumor (1); cervical cancer (1); gastric tumors (1); infection (1); leukemia (1); lymph node metastases (1); lymphoma (1); melanoma (1); multiple myeloma (1); myocarditis (1); Obesity (1); osteosarcoma (1); pancreatic ductal adenocarcinoma (1); prostate carcinoma (1); Stroke (1).